RNU6-749P (RNA, U6 small nuclear 749, pseudogene)
Gene: Small nuclear RNA gene on chromosome 15 (20,855,251 to 20,855,357, reverse strand). Ensembl gene ENSG00000238489.
Homologues: Orthologues: macaque U6 (92% identical), macaque U6 (90% identical), guinea pig U6 (79% identical), dog U6 (76% identical), pig U6 (68% identical). Paralogues in human: RNU6-631P (100% identical), U6 (100% identical), RNU6-1021P (99% identical), RNU6-286P (98% identical), U6 (98% identical), RNU6-127P (93% identical), RNU6-1239P (93% identical), RNU6-1268P (93% identical), RNU6-473P (93% identical), RNU6-617P (93% identical), RNU6-816P (93% identical), RNU6-848P (93% identical), and 1288 more.